SPACA5 (sperm acrosome associated 5)
Synonyms: SLLP-X; LYZL5; SLLP2; LYC5; UNQ6288; dJ54B20.3; PNPK6288
Gene: Protein-coding gene on chromosome X (48,004,336 to 48,009,733, forward strand). Ensembl gene ENSG00000171489.
Subcellular location: Secreted
Gene Ontology:
Molecular function: lysozyme activity
Biological process: fusion of sperm to egg plasma membrane involved in single fertilization
Cellular component: acrosomal vesicle; sperm flagellum; extracellular region
Homologues: Orthologues: chimpanzee SPACA5 (100% identical), macaque SPACA5 (97% identical), pig SPACA5 (79% identical), dog SPACA5 (77% identical), rabbit LYZE (75% identical), rat Spaca5 (75% identical), guinea pig LYZE (74% identical), mouse Spaca5 (70% identical), Drosophila melanogaster CG8492 (38% identical), Drosophila melanogaster CG7798 (31% identical), Drosophila melanogaster CG30062 (30% identical), Drosophila melanogaster CG11159 (30% identical), and 8 more. Paralogues in human: SPACA5B (100% identical), LYZL1 (42% identical), SPACA3 (42% identical), LYZL2 (41% identical), LYZ (40% identical), LYZL6 (40% identical), LYZL4 (34% identical), LALBA (28% identical).
Diseases named in the same sentence as SPACA5 in open-access papers:
SPACA5 is named in the same sentence as 4 diseases in open-access papers, as found by Europe PMC text mining. Sharing a sentence is not in itself a finding about the gene and the disease. The quoted sentences say what the papers report.
bladder cancer (1 paper, 2020). "Other genes were not reported in PC patients, but only SPACA5 is reported in bladder cancer (Zhang, Chen & Chen, 2016)." (PMID 33240632, 2020).
developmental delay (1 paper, 2015). "In a comparative genomic hybridization (CGH) array analysis a duplication of SPACA5 (and ZNF81/ZNF182) has been described in a boy with developmental delay, autistic features, and growth and speech delay." (PMID 25984793, 2015).
Infertility (1 paper, 2013). "The best candidate for a novel locus generating NAHR-mediated infertility risk mutations is a 100 kb segment on chromosome Xp11.23 flanked by two nearly identical (>99.5% homology) 16 kb segmental duplications containing the sperm acrosome gene SPACA5." (PMID 23555275, 2013).
SPACA5 also shares sentences with these, for which no sentence is quoted: speech delay (1 paper).